CCNA1 (cyclin A1)
Diseases named in the same sentence as CCNA1 in open-access papers (continued):
Sharing a sentence is not in itself a finding about the gene and the disease.
endometrial carcinoma (3 papers, 2015 to 2024). A malignant tumor arising from the epithelium that lines the cavity of the uterine body. "Cyclin A1 overexpression has already been described in a small set of EOC samples as well as in testicular germ cell tumors and endometrial cancer." (PMID 26499264, 2015). "CCNA1 is restricted to the germ line, while CCNA2 is ubiquitously expressed in all proliferating cells and is upregulated in a variety of cancers including endometrial cancer." (PMID 39264721, 2024). "Therefore, the miR-372/RhoC pathway and the miR-372/Cyclin A1 and CDK2 pathway may collectively be involved in the anti-oncogenic properties of miR-372 in endometrial carcinoma." (PMID 26673619, 2016).
cervical dysplasia (2 papers, 2013 to 2025). "For instance, the hypermethylation of CCNA1 and C13ORF18, both of which are key regulators of the cell cycle, is strongly associated with high-grade cervical intraepithelial neoplasia and cancer but is infrequent in normal or low-grade lesions." (PMID 40649795, 2025).
colorectal cancer (2 papers, 2009 to 2021). A primary or metastatic malignant neoplasm that affects the colon or rectum. "In colorectal cancer, up-regulation of LINC00467 reduces the expression of cyclin A1, cyclin D1, CDK2, CDK4 and Twist1, and enhances the expression of E-cadherin, thus promoting the development of colorectal cancer." (PMID 34888249, 2021). "A number of genes are commonly hypermethylated in colorectal cancer (CRC) including hMLH1, p16INK4a, p14ARF, RAR-β, APC, MGMT, cyclin A1, CDX1, MYOD1, COX-2 and WT-1." (PMID 19662090, 2009).
esophageal squamous cell carcinoma (2 papers, 2023 to 2025). Esophageal squamous cell carcinoma (ESCC) is a type of esophageal carcinoma (EC) that can affect any part of the esophagus, but is usually located in the upper or middle third. "Mechanistically, ZNF282 functions as a critical coactivator of E2F transcription factor 1(E2F1), transcriptionally upregulating the expression of cyclin A1 (CCNA1) and cell division cycle 6 (CDC6), thereby driving malignant progression in esophageal squamous cell carcinoma (ESCC)." (PMID 41331125, 2025).
head and neck cancer (2 papers, 2017 to 2021). A primary or metastatic malignant neoplasm affecting the head and neck. "The expression of CCNA1 has been found associated with poor prognosis in various cancers, including bladder urothelial carcinomas, oesophageal squamous cell carcinoma, as well as in head and neck cancer." (PMID 34290392, 2021). "Furthermore, HPV infection in e.g. head and neck cancers is associated with changes in the methylation profiles (or, increased methylation) of genes such as cyclin A1 that may in turn be related to LR and disease outcome." (PMID 28422732, 2017). "Interestingly, the corresponding proteins CCNA1, AREG or DDX20 have been individually found involved in a large range of solid tumours, including head and neck carcinoma." (PMID 34290392, 2021).
male infertility (2 papers, 2006 to 2008). The inability of the male to effect fertilization of an ovum after a specified period of unprotected intercourse. "Curiously, disruption of Cyclin A1 expression results in male infertility but not female infertility and specifically causes the developmental arrest of spermatogenesis during meiosis I." (PMID 18331635, 2008).
melanoma (2 papers, 2017 to 2024). A malignant, usually aggressive tumor composed of atypical, neoplastic melanocytes. "In 1007 melanoma cell line 1α-OH-vitD3 induced an increased expression of cyclin-A1 with slight up-regulation of p21 and p27 according to the accumulation of melanoma cells in the proliferative compartment (S plus G2 phase)." (PMID 28074906, 2017).
neuroblastoma (2 papers, 2016 to 2022). Neuroblastoma (NB) is the most common solid, extracranial childhood tumor. "When MYCN was knocked-down by RNAi in selected neuroblastoma cell lines, cyclin A1 (CCNA1, OMIM 604036) and cyclin G2 (CCNG2, OMIM 603203) were upregulated alongside the cyclin-dependent kinase inhibitor CDKN1C, suggesting a functional connection between MYCN amplification and cell cycle control." (PMID 35804856, 2022).
non-small cell lung carcinoma (2 papers, 2013 to 2020). A group of at least three distinct histological types of lung cancer, including non-small cell squamous cell carcinoma, adenocarcinoma, and large cell carcinoma. "Cyclin A1 plays an important role in enhanced cell proliferation in non-small cell lung cancer." (PMID 23941782, 2013).
Oral Squamous Cell Carcinoma (2 papers, 2021 to 2023). "This study aimed to investigate AITC’s impact on the KDM8/CCNA1 axis to elucidate its role in oral squamous cell carcinoma (OSCC) tumorigenesis." (PMID 37893043, 2023).
papillary thyroid carcinoma (2 papers, 2024 to 2025). "Specifically, noteworthy are our findings regarding the potential diagnostic value of CCNA1 and SFN genes in papillary thyroid carcinoma, while the reduced expression of CDKN1C, FOS, and JUN genes in follicular carcinoma suggests their value in distinguishing the thyroid pathologies." (PMID 40722651, 2025).
sterility (2 papers, 2023 to 2025). "Male Ccna1 (the gene encoding cyclin A1) knockout mice exhibit a block in spermatogenesis before the first meiotic division, resulting in sterility, while females are unaffected." (PMID 37686466, 2023). "Disruption of CCNA1 in male mice results in sub-fertility or sterility due to reduced sperm production." (PMID 40723324, 2025).
thyroid cancer (2 papers, 2018 to 2025). "Induction of apoptosis following CDK4/6 inhibition in thyroid cancer cells involved a modulation of FOXM1, cyclin A1 and myc." (PMID 30349650, 2018).
acute leukemia (1 paper, 2020). A clonal (malignant) hematopoietic disorder with an acute onset, affecting the bone marrow and the peripheral blood. "Overexpression of Cyclin A1 in murine hematopoietic stem cells caused myelodysplasia and acute leukemia, indicating its oncogenic potential, which makes downregulation, mutation, or deletion of Cyclin A1 as a resistance mechanism to immunological pressure by a targeted T cell therapy unlikely." (PMID 32157447, 2020).
Barrett esophagus (1 paper, 2023). Esophageal lesion lined with columnar metaplastic epithelium which is flat or villiform. "More recently, a test called “EsoGuard”, which is based on the methylation analysis of CCNA1 and VIM genes in brush cells for the detection of Barrett’s esophagus, which is the precursor and a major risk factor for esophageal adenocarcinoma, has recently received CE-IVD certification." (PMID 37511475, 2023).
caveolinopathy (1 paper, 2013). A group of muscle diseases with basis in CAV3, which encodes caveolin-3, a muscle-specific membrane protein and the principal component of caveolae membrane in muscle cells in vivo. "cDNA microarray data showed specifically elevated cyclin A1 levels in FSHD vs. other muscular disorders such as caveolinopathy, dysferlinopathy, four and a half LIM domains protein 1 deficiency and healthy controls." (PMID 24019929, 2013).
cervical (1 paper, 2020). "Sensitivity of high-grade cervical lesion detection in self-sampled CCNA1 promoter methylation test in this study was quite low (19.67%), but its specificity was as high as 99.54% and its accuracy was 82.14%." (PMID 33112548, 2020).
clear cell renal carcinoma (1 paper, 2023). A malignant epithelial neoplasm of the kidney characterized by the presence of lipid-containing clear cells within a vascular network. "For example, MCM8 and CCNA1, two cell cycle genes that are normally downregulated in clear cell renal carcinoma Caki-1/2 cells after exogenous PBRM1 expression, were significantly upregulated in PBRM1 knockdown cells that expressed PBRM1-BAHmut compared with PBRM1-BAHwt." (PMID 37394010, 2023).
depressed (1 paper, 2020). "Taken together, MYC might initiate the carcinogenesis of depressed neoplasms at the early stage, and subsequently, CCNA1 and BIRC7 might promote its invasiveness and further migration." (PMID 32532105, 2020).
dysferlinopathy (1 paper, 2013). "In this article we present evidence of cyclin A1 overexpression at both RNA and protein level in FSHD-1, but not in other muscular dystrophies such as caveolinopathy 3 (CAV 3), dysferlinopathy (DYSF) and four and a half LIM domains protein 1 deficiency (FHL1)." (PMID 24019929, 2013).
esophageal cancer (1 paper, 2025). A primary or metastatic malignant neoplasm involving the esophagus. "Their molecular cytology assay, based on a two-marker panel of mVIM and CCNA1, detected BE and EAC with over 90% sensitivity and specificity, showing the utility of DNA methylation markers in esophageal cancer surveillance." (PMID 40149421, 2025).
facioscapulohumeral muscular dystrophy (1 paper, 2013). An autosomal dominant disorder affecting the skeletal muscles of the face, scapula, and upper arm. "Altered cyclin A1 expression might contribute to clinical symptoms in facioscapulohumeral muscular dystrophy (FSHD)." (PMID 24019929, 2013).
glioblastoma (1 paper, 2022). The most malignant astrocytic tumor (WHO grade IV). "The CCNA1/CCNB1/CDK1/p21CIP1 pathway is associated with G2/ M-phase arrest in glioblastoma cells." (PMID 35246013, 2022).
HIV-1 infection (1 paper, 2005). The type species of lentivirus and the etiologic agent of acquired immunodeficiency syndrome (AIDS). "Several genes have been established as important for HIV-1 infection and replication, including Pou2AF1 (OBF-1), complement factor H related 3, CD4 receptor, ICAM-1, NA, and cyclin A1." (PMID 15780141, 2005). "As observed in both tables and the initial screening of genes displaying at least two present calls, several genes have been established as important for HIV-1 infection and replication, including OBF-1, complement factor H related 3, CD4 receptor, ICAM-1, NA, and cyclin A1." (PMID 15780141, 2005).
injury (1 paper, 2024). Damage inflicted on the body as the direct or indirect result of an external force, with or without disruption of structural continuity. "In this study, we found that the HuR protein expression was inducible in the mouse model of APAP‐induced liver injury and found that HuR could protect against APAP‐induced liver injury by promoting the expression of NRF2, cyclin A1, cyclin B1, cyclin D1, CDK2, ATG3, ATG5 and ATG7." (PMID 39614424, 2024).
invasive carcinoma (1 paper, 2025). A carcinoma that is not confined to the epithelium, and has spread to the surrounding stroma. "DNA methylation patterns involving genes like CCNA1, C13ORF18, DAPK, HIC-1, HIN-1, MGMT, RAR-beta, and RASSF1A were also modeled as influential epigenetic factors affecting different transition states from normal tissue to invasive carcinoma." (PMID 40649795, 2025).
osteoporosis (1 paper, 2024). A condition of reduced bone mass, with decreased cortical thickness and a decrease in the number and size of the trabeculae of cancellous bone (but normal chemical composition), resulting in increased fracture incidence. "Therefore, we aims to seek for the function of CCNA1 and the underlying mechanisms in osteoporosis, thereby to open up new ideas for the treatment of osteoporosis and other bone metabolism-related diseases." (PMID 38454404, 2024). "Earlier bioinformatics analysis results demonstrated that CCNA1 was aberrant expressed gene in osteoporosis." (PMID 38454404, 2024). "Cyclin A1 (CCNA1) was found to be significantly upregulated in serum of osteoporosis patients and the osteoporosis model cells, which was in line with the bioinformatic analysis." (PMID 38454404, 2024). "Then, expression levels of SMAD2/3 and phosphorylated SMAD2/3 were notably increased induced by silenced CCNA1 in DEX-induced osteoporosis cells." (PMID 38454404, 2024). "Additionally, the mRNA expression of CCNA1 was upregulated in the serum of patients with osteoporosis compared with the normal group." (PMID 38454404, 2024). "Moreover, the knockdown of CCNA1 significantly promoted osteogenesis in DEX-induced osteoporosis cells." (PMID 38454404, 2024). "Our data suggested that CCNA1 screened from the bioinformatics analysis was dramatically overexpressed in the serum of patients with osteoporosis, indicating that CCNA1 may be a potential gene related to bone metabolism." (PMID 38454404, 2024). "Knockdown of CCNA1 may be an potential therapy for osteoporosis." (PMID 38454404, 2024). "Furthermore, the TGF-beta signaling pathway inhibitor LY2109761 significantly suppressed osteogenesis promoted by silenced CCNA1 in DEX-induced osteoporosis cells, suggesting that CCNA1 suppressed osteoblast differentiation by inactivating TGF-beta signaling pathway in osteoporosis." (PMID 38454404, 2024). "Moreover, whether CCNA1 regulate the process of osteoporosis in a DEX-induced mouse model should also be studied." (PMID 38454404, 2024). "Downregulation of CCNA1 could activate TGF-beta signaling pathway and promote bone formation, thus playing a role in treatment of osteoporosis." (PMID 38454404, 2024).
schizophrenia (1 paper, 2024). A major psychotic disorder characterized by abnormalities in the perception or expression of reality.
seminoma (1 paper, 2024). A radiosensitive malignant germ cell tumor found in the testis (especially undescended), and extragonadal sites (anterior mediastinum and pineal gland). "Focal deletions spanning cyclin A1 (CCNA1) and the transcription factor FOXO1 (13q13.3), critical for successful spermatogenesis, were found to occur exclusively in seminomas." (PMID 39461959, 2024).
squamous cell carcinoma (1 paper, 2023). A carcinoma arising from squamous epithelial cells. "Sm4-mediated cell cycle arrest showed S-phase cell accumulation, which differed among squamous cell carcinoma and lung and adenocarcinoma cell lines due to the opposing results of cyclin A1 expression." (PMID 37511076, 2023). "The difference in the observed cell cycle phases distribution between squamous cell carcinoma and lung and adenocarcinoma cell lines may be explained by the opposing results of cyclin A1 expression, which is responsible for the S-to-G2/M phase transition." (PMID 37511076, 2023).
squamous intraepithelial lesion (1 paper, 2018). "At the same time, CCNA1 promoter methylation serves as a potential marker for distinguishing between histologic LSIL (low-grade squamous intraepithelial lesion)/negative and HSIL (high-grade squamous intraepithelial lesion)/positive." (PMID 29850477, 2018).
thyroid (1 paper, 2025). "In the comparison between PTC and benign thyroid samples, SFN and CCNA1 were significantly upregulated, whereas FOS, HSPA5, JUN, CREB1, and MAP2K6 exhibited significant downregulation, supporting the findings obtained from the RT-qPCR analysis." (PMID 40722651, 2025).
cancer (65 papers, 2006 to 2025). A tumor composed of atypical neoplastic, often pleomorphic cells that invade other tissues. "Dysregulation of Cyclin A1 has been implicated in various cancers including breast and thyroid cancers." (PMID 38553531, 2024). "The overexpression of CCNA1 has been linked to unfavorable prognoses in various cancers, including bladder urothelial carcinomas, esophageal squamous cell carcinoma, as well as head and neck cancer." (PMID 37893043, 2023). "Cyclin A1 regulates both the G1-S and G2-M checkpoints, correlates with degree of dysplasia in BE patients and is linked to cancer invasiveness." (PMID 26378019, 2015). "Cyclin A1 expression enhances G1/S transition in somatic cells and is associated with enhanced proliferation and invasiveness in cancers of the breast, prostate, urothelium, and thyroid." (PMID 26499264, 2015). "In contrast, the genes encoding cyclin-A1, -B1, -E1 and -E2, i.e. Ccna1, Ccnb1, Ccne1 and Ccne2, were up-regulated in malignant tumors." (PMID 25900242, 2015). "However, accumulating evidence indicates that upregulation of CCNA1 is closely associated with cancer development, progression, and metastasis in several types of tumors, including EC37–39." (PMID 37612452, 2023). "Some genes, such as CDKN2B and CCNA1, exhibited inconsistent expression patterns across different cancer types, suggesting dynamic expression across tissues." (PMID 40149461, 2025). "Hallmark Apoptosis (Overlap Genes: CCNA1, NEFH, ERBB2): Apoptosis or programmed cell death is critical in cancer progression." (PMID 39000413, 2024). "Hyper-methylated genes included previously reported targets of recurrent hyper-methylation in OSCC, such as DDAH2, CCNA1, DCC, as well as some cancer-associated genes including HRAS." (PMID 38589501, 2024). "In the cancer pathway, cell-cycle gene cyclin A1 and cyclin D1 were upregulated, while tumor proliferation and metastasis pathway FAK-PI3K and Ras-PI3K were upregulated; DNA damage repair-related gene RAD51 was also upregulated." (PMID 36090994, 2022). "Although this study did not explore a tumor model, the presented results open up new avenues for research on cancer and various pathologies, as well as PPARγ activity and CCNA1." (PMID 35256739, 2022). "The objective of this study was to evaluate the value or ability of self-sampled CCNA1 promoter methylation (SS-CCNA1) for the detection of high-grade cervical precancerous and cancerous lesions (≥ CIN2)." (PMID 33112548, 2020). "High expression of cyclin A1 has been observed in various cancers and was correlated with proliferative activity and enhanced tumor growth." (PMID 33324557, 2020). "Although numerous studies have shown the critical roles of cyclin A1 and p27 in regulating cell cycle progress in various cancer, however, the likely molecular regulation mechanism by which HK2 mediated cyclin A1 and p27 expression is less known." (PMID 33324557, 2020). "To further study its role in liver malignancy, we examined the expression of several cyclin family members in large scale cancer datasets provided by TCGA, including CCNA1, CCND1, and CCNE1." (PMID 31349793, 2019). "Ccna1 is chiefly expressed in meiotic and cancer cell cycles, while A2 and E1 drive the G1 to S phase transition and the S phase events of centriole and DNA duplication." (PMID 30152757, 2018). "RT-PCR and Western blot assays detected the expression of known targets of miR-372 in other malignant tumors and found Cyclin A1 and Cyclin-dependent Kinase 2 (CDK2) was downregulated by miR-372." (PMID 26673619, 2016). "Cyclin A1 fulfills this criterion, being homogenously expressed at a moderate to high level in more than half of the high-grade carcinomas analyzed." (PMID 26499264, 2015). "Tissue-specific antigens that are recruited and expressed by cancers in specific tissues (e.g. cyclin-A1 or Cancer/Testis Antigen 1B)." (PMID 25521819, 2014).